IL17A (interleukin 17A)
Diseases named in the same sentence as IL17A in open-access papers (continued):
Sharing a sentence is not in itself a finding about the gene and the disease.
Peritoneal Fibrosis (12 papers, 2014 to 2024). Disorder characterized by a wide range of structural changes in PERITONEUM, resulting from fibrogenic or inflammatory processes. "Moreover, weekly IL-17A intraperitoneal injections for 35 days induced peritoneal fibrosis characterized by PM thickness associated with fibronectin deposition and expression of myofibroblast markers, such as fibroblast-specific protein 1 (FSP-1) and α-smooth muscle actin (α-SMA)." (PMID 32987705, 2020). "In both models of PDF exposure, the contribution of IL-17A to the peritoneal damage was demonstrated by using intraperitoneal neutralizing anti-IL-17A antibodies that decreased peritoneal fibrosis." (PMID 32987705, 2020). "All these processes promoted by IL-17A contribute to PM thickening and to peritoneal fibrosis progression, suggesting a potential key role of IL-17 in PM fibrosis." (PMID 32987705, 2020). "In peritoneal biopsies from these PD patients, submesothelial IL-17A immunostaining was found mainly in inflammatory and fibrotic areas and correlated with peritoneal fibrosis." (PMID 32987705, 2020). "As pointed out before, peritoneal IL-17A administration to mice induced peritoneal fibrosis, characterized by fibronectin accumulation and submesothelial FSP-1 and α-SMA-stained cells." (PMID 32987705, 2020). "Regarding peritoneum, IL-17A could contribute to peritoneal fibrosis by direct effects on resident fibroblasts." (PMID 32987705, 2020). "On the other hand, the use of a neutralizing IL-17A antibody injected intraperitoneally in mice exposed to PDF for 35 days blockaded the anatomical changes in the PM and reduced peritoneal fibrosis." (PMID 26064907, 2015). "Interestingly, in experimental PDF exposure, the IL-17A blockade prevented the induction of MMT markers, such as α-SMA, and peritoneal fibrosis." (PMID 32987705, 2020). "Paricalcitol, an analog of vitamin D and a specific activator of vitamin D receptors (VDR), reduced PDF-induced peritoneal fibrosis in murine PD and decreased peritoneal IL-17A levels but not of other cytokines, including IL-1β, IL-2, IL-4, IL-5, IL-6, IL-10, TNF-α, IFN-γ, and TGF-β1." (PMID 32987705, 2020).
rhinitis (12 papers, 2013 to 2024). An inflammation of the mucous membrane lining the nose, usually associated with nasal discharge. "Although it was significantly decreased in the lesions of AD patients with AR, its expression level was barely related to serum IL17A or rhinitis severity." (PMID 33868246, 2021).
staphylococcal infection (12 papers, 2016 to 2025). An infection caused by Staphylococcus. "Elevated levels of G-CSF and IL-17A are linked to increased quantitative and potent neutrophil responses in staphylococcal infection, suggesting component 2 may correspond to a neutrophil dysfunction." (PMID 38779114, 2024). "Interestingly, it has been shown that immunization with ClfA combined with an alum adjuvant failed to confer protection against systemic infection in IL-17A deficient mice, further highlighting the importance of an IL-17 response in protection against Staphylococcal infections." (PMID 26901227, 2016).
viral hepatitis (12 papers, 2017 to 2025). An acute or chronic inflammation of the liver parenchyma caused by viruses. "IL-17A promotes a proinflammatory and profibrotic environment in response to chronic viral hepatitis, triggering more tissue injury and dysfunctional reparative responses." (PMID 30400258, 2018). "In patients with chronic viral hepatitis, neutrophils accounted for most of the IL-17A+ cells, especially in the late fibrosis stage, but the frequency of CD45+IL-17A+ lymphocytes in liver tissue was independent of the stage of fibrosis (F0–F3)." (PMID 34211477, 2021).
atrial fibrillation (11 papers, 2015 to 2025). A disorder characterized by an electrocardiographic finding of a supraventricular arrhythmia characterized by the replacement of consistent P waves by rapid oscillations or fibrillatory waves that vary in size, shape and timing and are accompanied by an irregular ventricular response. "Therefore, alongside CRP and NLR, preoperative IL-17A can be considered a potentially significant marker for atrial fibrillation following cardiac surgery." (PMID 40599146, 2025).
basal cell carcinoma (11 papers, 2020 to 2025). A carcinoma involving the basal cells. "Basal cell carcinoma cell line did not express the IL-17A gene, while the expression of the other genes examined was significantly upregulated only after 4 h of treatment with 1,25(OH)2D3." (PMID 34884710, 2021).
brain injury (11 papers, 2018 to 2026). Acute and chronic (see also brain INJURIES, CHRONIC) injuries to the brain, including the cerebral hemispheres, CEREBELLUM, and brain STEM. "Furthermore, the involvement of IL-17A signaling has been revealed in various experimental models of ischemic brain injury, traumatic brain injury, and spinal cord injury." (PMID 35211045, 2022).
chronic granulomatous disease (11 papers, 2014 to 2025). Chronic granulomatous disease (CGD) is a rare primary immunodeficiency, mainly affecting phagocytes, which is characterized by an increased susceptibility to severe and recurrent bacterial and fungal infections, along with the development of granulomas. "PBMC from patients with chronic granulomatous disease exhibited a lower IL-17A production upon stimulation with Aspergillus and Candida compared to healthy donors, and this might contribute to ineffective fungal clearance in these patients." (PMID 29371571, 2017).
ichthyosis (11 papers, 2020 to 2025). Disorders of cornification that are characterized by visible scaling and/or hyperkeratosis of most or all of the skin. "This not only shows the great potential of Vunakizumab in treating ichthyosis but also paves the way for further research on anti-IL-17A therapies for skin cornification disorders, offering treatment options for ichthyosis patients." (PMID 40453098, 2025). "A 48% IASI reduction and decreased proinflammatory cytokines suggest IL-17A inhibition as a promising and well-tolerated treatment for ichthyosis." (PMID 40734872, 2025). "This study is the first to report the use of Vunakizumab, China's first self-developed anti-IL-17A monoclonal antibody, in treating ichthyosis." (PMID 40453098, 2025). "In different forms of congenital ichthyosis the use of anti IL-17 A antibody and an IL-12/IL-23 antagonist have been proposed with promising results, based on an IL-17–skewed inflammatory signature revealed in these patients." (PMID 37033173, 2023). "The IASI-E (Ichthyosis Area and Severity index—erythema) score showed a significant correlation with IL-17A levels and TEWL." (PMID 35840979, 2022). "Currently, the repurposing drugs in ichthyosis are focused on the use of drugs that inhibit factors related to immune system molecules such as TNF-α (infliximab, adalimumab), IL-17A (Secukinumab, Ixekizumab), IL-4, IL-12, IL-23 (Dupilumab), and IL-36." (PMID 38027029, 2023).
lupus erythematosus (11 papers, 2013 to 2025). An autoimmune, connective tissue chronic inflammatory disorder affecting the skin, joints, kidneys, lungs, heart, and the peripheral blood cells. "Moreover, SHP2 is an important mediator in lupus erythematosus, ERK/MAPK signaling normalization and reduced production of IFN-γ and IL-17a cytokines involved in inflammation can occur by directly inhibiting SHP2." (PMID 34456714, 2021).
mucositis (11 papers, 2014 to 2025). Mucositis is inflammation and damage of the mucous membranes lining the mouth and other parts of the gastrointestinal (GI) tract. "Roles of CD4+/IL-17A lymphocytes on intestinal immunity and the pathophysiology of chemotherapy-induced mucositis have been investigated recently." (PMID 33564301, 2021).
myocardial ischemia (11 papers, 2015 to 2025). A disorder of cardiac function caused by insufficient blood flow to the muscle tissue of the heart. "IL-34 regulates the expression of proinflammatory cytokines (IL-17A, IL-1 and IL-6), which are classical cytokines involved in myocardial ischemia‒reperfusion (MI/R) injury." (PMID 39883639, 2025). "In myocardial ischemia, depletion of IL-17A or γδ T cells has been shown to improve the survival rate of mice after early myocardial ischemia." (PMID 38774876, 2024). "Another study found that IL-17A knockout or γδT cell ablation can improve the survival rate of mice after 7 days, indicating that IL-17A is involved in early myocardial ischemia-re-perfusion injury." (PMID 37600023, 2023). "Although 70% of IL-17A is expressed by Th cells, the differentiation of naive CD4 + T cells into Th17 cells takes a long time and cannot produce a large amount of IL-17A in a process similar to myocardial ischemia." (PMID 37600023, 2023). "HMGB1 promoting IL‐17A release has been shown in myocardial ischemia–reperfusion injury." (PMID 38414294, 2024). "The supplement of exogenous IL-17A aggravated myocardial ischemia-re-perfusion injury." (PMID 37600023, 2023). "In addition, other experiments have shown that IL-17A levels are significantly increased in myocardial ischemia–reperfusion injury, inflammation, and apoptosis." (PMID 36253831, 2022). "At the same time, studies have also confirmed that anti-IL-17A monoclonal neutralizing antibody treatment or IL-17A knockout significantly reduced neutrophil infiltration and inhibited cardiomyocyte apoptosis, significantly improving myocardial ischemia-re-perfusion injury." (PMID 37600023, 2023). "High levels of IL17A and up-regulated JAK2-STAT3 signaling pathway can promote inflammatory reactions, induce cardiomyocyte apoptosis, and ultimately aggravate myocardial ischemia and reperfusion (I/R) injury." (PMID 37564653, 2023).
nasopharyngitis (11 papers, 2021 to 2025). An inflammatory process that affects the nasopharynx. "Biologics targeting IL-17A, IL-17A/F, and IL-17R were the most common causes of nasopharyngitis, with incidence rates of 16.05%, 12.62%, and 10.27%, respectively." (PMID 36817423, 2023). "Comparing to placebo, IL-17A inhibitors increased the risk of nasopharyngitis (OR = 1.72; 95% CI, 1.15 to 2.57; p < 0.01)." (PMID 33432451, 2021). "Compared to placebo, IL-17A inhibitors improved ASAS20 response rate (OR = 2.58; p < 0.01) and ASAS40 response rate (OR = 2.80; p < 0.01), and significantly increased the risk of AEs (OR = 1.23; p = 0.03) and nasopharyngitis (OR = 1.72; p < 0.01), but not SAEs (OR = 0.87; p = 0.60)." (PMID 33432451, 2021).
Neonatal sepsis (11 papers, 2017 to 2024). Systemic inflammatory response to infection in newborn babies. "Research exhibited that IL-17A participated in the process of LPS-induced inflammatory response and that the IL-17A antibody reduced the mortality rate of neonatal sepsis." (PMID 38791080, 2024). "In a neonatal sepsis mice model, treatment with IL-17A-neutralizing antibody mitigated IL-18-related disease deterioration." (PMID 32849528, 2020). "For instance, interleukin (IL)-17A is recognized as a effector of IL-18–mediated injury and the outcomes of neonatal sepsis can be improved by disrupting the IL-18/IL-1/IL-17A axis." (PMID 30497506, 2018). "The deleterious effects of IL-18 on neonatal sepsis survival were dependent upon IL-1R1 signaling and IL-17A production by gamma delta cells in the intestine and lung." (PMID 28224121, 2017). "Targeting the IL-18/IL-17A axis through the use of neutralizing IL-17 receptor antibodies represents a novel approach to treating neonatal sepsis." (PMID 28224121, 2017).
oral cancer (11 papers, 2014 to 2025). "Then it was discovered that IL-17A rs2275913 acted as risk factors for gastric, cervical, colorectal and oral cancer, and IL-17F rs763780 for cervical and oral cancer." (PMID 36300118, 2022). "In addition, it has been shown that C. albicans promotes development of 4NQO-induced oral cancer via the IL-17A/IL-17RA induced tumor associated macrophages." (PMID 37373022, 2023). "In addition, the study shows that C. albicans-induced IL-17A/IL-17RA signaling promotes the growth of oral cancer xenografts in vivo." (PMID 37374978, 2023). "In the previous paper, it was pointed out that IL-17A rs2275913 acted as risk factor for multiple cancers (gastric, cervical, colorectal and oral carcinoma) and non-cancerous diseases (RA)." (PMID 36300118, 2022). "Consequently, the increased IL-17A/IL-17RA signaling activates macrophages and promotes the release of inflammatory cytokines, which in turn enhances the proliferation, migration, and invasion of oral cancer cells." (PMID 37374978, 2023). "A recent study also highlighted that the salivary levels of interleukin 17A (IL-17), interleukin 17B (IL-17B), and TNF-α were strictly related to oral cancer progression." (PMID 36005828, 2022).
oral lichen planus (11 papers, 2013 to 2025). Oral lichen planus is a chronic inflammatory oral condition of unknown aetiology characterized by T-cell-mediated chronic immune response and abnormal epithelial keratinization cycle. "For instance, research on the relationship between IL‐17A and oral lichen planus reported serum IL‐17A levels ranging from 8.242–28.663 pg/mL in healthy controls and 8.242–92.282 pg/mL in patients with oral lichen planus." (PMID 39946217, 2025). "Elevated serum IL‐17A levels have been observed in a variety of inflammatory and metabolic diseases, including psoriasis, oral lichen planus and systemic lupus erythematosus." (PMID 39946217, 2025). "IL-17A-producing cells were detected at the highest levels in CHC and oral lichen planus and were most prevalent in the corium." (PMID 34209407, 2021).
prostatitis (11 papers, 2013 to 2024). An infectious or non-infectious inflammatory process affecting the prostate gland. "The interplay between IL‐17A and CCL20 establishes a positive feedback loop, which might serve as a critical mechanism underpinning the development of chronic prostatitis, thus adding complexity to its treatment challenges." (PMID 38801403, 2024).
psychosis (11 papers, 2019 to 2025). "Furthermore, olanzapine seems to have marginal immunomodulatory effects in drug naïve patients in the first episode of psychosis, regulating the expression of genes related to the immune system, such as IL-17A and IL-20." (PMID 37206523, 2023).
vulvovaginal candidiasis (11 papers, 2011 to 2026). Infection of the vulva and vagina with a fungus of the genus CANDIDA. "The KFXL has efficient antifungal activity against vulvovaginal candidiasis in mice in two ways: by inhibiting mycelia growth and development to reduce C. albicans colonization, and by promoting the secretion and release of IL-17A and neutrophils to fight C. albicans infection." (PMID 40264666, 2025).
acute GVHD (10 papers, 2011 to 2026). "In this study, we dissect the role of donor-derived IL-17A and IL-17F for endothelial and epithelial permeability in an experimental acute GVHD model using single- (Il17a-/-, Il17f-/-) and double-deficient (Il17af-/-) donor T cells." (PMID 32251446, 2020). "To date, Janus-head roles taken by Th17 and associated cytokines such as IL-17A and IL-22 during acute GVHD have been documented In one study, IL-17A deficiency led to disease reduction, whereas another study showed that the absence of IL-17A- secreting cells exacerbated GVHD." (PMID 32251446, 2020). "Given the known ability of IL-17 to maintain epithelial cell barrier function, the authors conclude that riboflavin metabolite sensing MAIT cells regulate acute GVHD at least partially via IL-17A secretion." (PMID 30705680, 2018). "Therefore, our data points to potential redundancy of IL-17A and IL-17F in the pathology of acute GVHD." (PMID 32251446, 2020). "In contrast, elevated IL-6, IL-17A, PAI-1, IL-10, CX3CL1, CXCL1, and CCL4 levels were prognostic for quiescent cGVHD compared with patients with resolved acute GVHD only." (PMID 41798937, 2026). "During acute GVHD, MAIT cells generated large amounts of IL-17A, enhanced intestinal barrier function and reduced GI GVHD severity." (PMID 30705680, 2018). "Since the IL-17 isoforms A and F both bind to the IL-17RA receptor, we checked whether either lack of IL-17A or F altered protection from acute GVHD." (PMID 32251446, 2020). "Furthermore, gut stem cell recovery is affected in the absence of donor-derived IL-17A and F. Such response results in aggravated acute GVHD." (PMID 32251446, 2020).
acute lung injury (10 papers, 2017 to 2025). A condition of lung damage that is characterized by bilateral pulmonary infiltrates (pulmonary edema) rich in neutrophils, and in the absence of clinical heart failure. "miR-146b ameliorates LPS-induced acute lung injury, whereas its reduction increases IL-17A and promotes T cell acute lymphoblastic leukemia cell migration and invasion." (PMID 33182773, 2020).
age-related macular degeneration (10 papers, 2011 to 2026). Age-related loss of vision in the central portion of the retina (macula), secondary to retinal degeneration. "A recent study of age-related macular degeneration (AMD) reported that IL-17A induces IL-1β secretion from retinal pigment epithelium (RPE) cells via NLRP3 inflammasome activation." (PMID 37109536, 2023).
alcoholic hepatitis (10 papers, 2011 to 2025). Acute hepatitis resulting from ingestion of alcohol. "IL-17A augmented ER stress has been implicated in some organ damage, including LPS-induced lung injury, intracerebral hemorrhage, alcoholic hepatitis." (PMID 33933165, 2021). "However, in another study, it was found that OPN deficiency does not decrease the incidence of alcoholic hepatitis and expression of fibrogenic genes, but promotes the generation of IL-17a and neutrophil infiltration in mice receiving alcohol." (PMID 31244862, 2019).
amyloidosis (10 papers, 2018 to 2025). A disorder characterized by the localized or diffuse accumulation of amyloid protein in various anatomic sites. "In the current study, we showed that IL-17A is an essential cytokine for amyloidosis of the liver and spleen associated with cutaneous inflammation." (PMID 35628531, 2022). "Amyloidosis in both liver and spleen was ameliorated in IL-17A-/KCASP1Tg mice, and the expression level of SAA in the liver was decreased compared with 16-week-old KCASP1Tg mice." (PMID 35628531, 2022). "Amyloidosis in the spleen was ameliorated in IL-17A-/KCASP1Tg and IL-17AF-/KCASP1Tg mice." (PMID 39519167, 2024). "Amyloidosis was ameliorated in IL-17A-/KCASP1Tg and IL-17AF-/KCASP1Tg mice." (PMID 39519167, 2024). "Moreover, KCASP1Tg mice were crossed with interleukin-17A (IL-17A) knockout mice to generate IL-17A-/KCASP1Tg and examine the role of IL-17A in amyloidosis under cutaneous inflammation." (PMID 35628531, 2022). "Interestingly, IL-17A is responsible for the formation of amyloidosis in both the liver and the spleen, a disorder in which abnormal proteins accumulate." (PMID 36591277, 2022). "Overproduction of amyloidosis was partially ameliorated by the administration of JAK inhibitors and was further improved in IL-17A-/KCASP1Tg mice." (PMID 35628531, 2022). "Amyloidosis in the liver was recovered in IL-17A-/KCASP1Tg mice and IL-17AF-/KCASP1Tg mice but not in IL-17F-/KCASP1Tg mice." (PMID 39519167, 2024). "While by inhibiting RORγt in 27-OHC-loaded mice, Th17 proportions in both PBMCs and hippocampus were reduced, and expressions of IL-17A and TGF-β1 were down- and up-regulated, respectively, along with a decreased amyloidosis in brain and improved learning and memory decline." (PMID 38115100, 2023).